CDK5 (cyclin dependent kinase 5)
Diseases named in the same sentence as CDK5 in open-access papers (continued):
Sharing a sentence is not in itself a finding about the gene and the disease.
tumor (continued). "Therefore, directing CDK5 to the nucleus or exporting tumor-suppressive nuclear substrates to the cytoplasm may be promising approaches to combat CDK5-induced oncogenicity, analogous to neurotoxicity triggered by nuclear CDK5." (PMID 37993880, 2023). "Moreover, in vivo antitumour effect of Cdk5 gene manipulation by intravenous injection silent 95% genetic expression of Cdk5, which decreased 75.7% tumour weight, 89.6% tumour volume, protein expression profile, and messenger RNA expression, than anti-PD-L1 antibody and PBS control group." (PMID 36267139, 2022). "While these studies show that tumors retain dependence upon Cdk5 activity for sustained growth, the variability in age of onset combined with 75% penetrance by 12 months of age raises the possibility that additional alterations occur and facilitate tumor formation." (PMID 34862365, 2021). "Thus, inhibiting Cdk5 suppresses tumor growth and improves survival." (PMID 34814918, 2021). "CDK5 may phosphorylate tumour suppressors and transcriptional factors." (PMID 33396266, 2020). "This raises the question of whether CDK5 manipulates tumour development through glucose uptake." (PMID 33396266, 2020). "CDK5 may modulate tumour development and metastasis through neurotransmitters." (PMID 33396266, 2020). "Meanwhile, the CDK5 staining occurring in cytoplasm could be found on most tumor cells." (PMID 31496920, 2019). "Thus, CDK5 plays a significant role in tumor progression and metastasis." (PMID 31272499, 2019). "However, in endothelial Cdk5 knockout mice anti-VEGF treatment diminished tumor growth." (PMID 26755662, 2016). "Furthermore, CDK5 might promote proliferation, tumor formation and invasion of CRC partly via modulating the ERK5–AP-1 signaling axis." (PMID 27735944, 2016). "Given the important role of LIMK1 and CDK5 in tumor metastasis, the LIMK1 inhibitor BMS‐5 and CDK5 inhibitor Dinaciclib were employed to evaluate the potential of targeted therapy." (PMID 40476449, 2025). "Clinically, this Cdk5-mediated activation of the DDR leads to therapeutic resistance, establishing Cdk5 as a key factor in tumor cell survival under genotoxic stress." (PMID 41369365, 2025). "Among the 50 most notable DEGs related to ERS displayed in the heatmap, we observed that 26 ERS regulators were dramatically up-regulated in tumor samples, with PPP1CA, CDK5, and TMED9 showing fold changes of 1.25, 1.67, and 1.05, respectively." (PMID 38440732, 2024). "We have previously reported that CDK5 phosphorylates KDR (Ser‐229) and that Pit‐1 (Ser126) can directly promote tumor cell proliferation and invasion." (PMID 38363020, 2024). "Tumor burden quantification revealed that concurrent ERK5 and CDK5 inhibition cooperated in suppressing lung tumor burden compared to vehicle or single treatment cohorts." (PMID 39271958, 2024). "We further revealed that the increased sensitivity of tumor cells to oxaliplatin induced by CDK5 was restored by E2F1 knockdown, suggesting that CDK5-induced chemosensitivity is dependent on E2F1." (PMID 37990321, 2023). "Higher levels of CDK5 in CRC correlate with advanced disease stage, poor differentiation, increased tumor size and poor prognosis." (PMID 37993880, 2023). "Phosphorylation at Ser267 of ACSS2 by CDK5 inhibits the degradation of ACSS2 and promote the growth of GBM tumor cells." (PMID 37143582, 2023). "The result also showed that CDK1, CDK5, CDC20, CCNA2, CCNB1 and CCNB2 mRNA expression levels within tumor tissues were significantly increased compared with the adjacent normal tissues." (PMID 36605491, 2023). "Cell trajectories showed that the expression of PRKCD, PRKAA2, CDK5, and CDK1 genes increased from hepatocytes to tumor cells." (PMID 36120466, 2022). "We then examined the expression of 9 model genes in single cells and found that CDK1, AURKB, CCNA2, and CHEK1 are mainly expressed in CD4 cells, while PRKAA2, CDK5, and PRKCD are mainly expressed in tumor cells." (PMID 36120466, 2022).
tumor (continued). "Cdk5 induces FAK phosphorylation at Ser732, a component of mitosis and spindle formation in tumor cells." (PMID 36120466, 2022). "We found that PRKCD, PRKAA2, CDK5, and CDK1 genes were increased in the progression from hepatocytes to tumor cells." (PMID 36120466, 2022). "Cyclin Dependent Kinase 5 (CDK5) is also a key molecule in regulating cell cycle, and downregulation of CDK5 can inhibit the expression of PDL1 and promote anti-tumor immunity." (PMID 36713456, 2022). "CDK5 silencing via transfection can directly reduce the proliferation of human HCT116 and SW480 tumor cell lines." (PMID 35002699, 2021). "Based on the GEPIA database, we observed that expression levels of Notch1, CDK5, p35, and p39 are higher in PDAC tumor tissues than in normal tissues." (PMID 33960694, 2021). "In a recent study, a novel CRISPR‐Cas9 system was used to knock out the cyclin‐dependent kinase 5 gene (CDK5), leading to the downregulation of PD‐L1 expression on tumor cells while promoting the population of cytotoxic effector cells in the TME." (PMID 34188916, 2021). "CDK5 expression is also reported to be much higher in CRC cells compared to normal epithelium and it correlates to increased tumor growth and poor prognosis." (PMID 35002699, 2021). "Vitro experiments show that vascular endothelial CDK5 inhibitors can influence the migration and proliferation of vascular endothelial cells by inhibiting NOTCH-driven angiogenesis, thereby affecting tumor angiogenesis and ultimately inhibiting tumor growth." (PMID 33346796, 2021). "In MB mouse models, disruption of CDK5 expression led to strong tumor rejection mediated by CD4 + T cells, highlighting an important role for CDK5 in immune checkpoint regulation." (PMID 33101383, 2020). "The depletion of CDK5 in medulloblastoma xenograft model resulted in diminished PD-L1 expression and increased the numbers of CD4+ tumour-infiltrating lymphocytes, resulting in robust CD4+ T-cell-mediated tumour rejection." (PMID 31910742, 2020). "The copy number analysis of CCA tumor samples indicated a gain in CDK2 (22.8%), CDK5 (14.3%), and CDK9 (5.7%)." (PMID 33116269, 2020). "We found that the tumor size and numbers in DEN-induced Cdk5+/− mice were much lesser than those in WT mice." (PMID 31272499, 2019). "Accumulated data have shown that CDK5 is an atypical CDK and critical for tumor growth in several types of human cancers." (PMID 31488827, 2019). "We could successfully translate our results into a clinical setting as high levels of Cdk5 were associated with a higher risk of relapse in early-stage MSS CRC patients that did not receive any treatment after primary tumor resection, especially in patients with KRAS-mutant tumors." (PMID 31614664, 2019). "The level of SOX2 also correlated with the tumor size and expression of epidermal growth factor receptor (EGFR) and cyclin-dependent kinase 5/6 (CDK5/6)." (PMID 31681564, 2019). "In this study, we confirmed that CDK5 is increased in HCC tissues and is related to tumor recurrence, vessel invasion, and survival of patients." (PMID 31272499, 2019). "A tumor suppresser protein CDK5RAP3, which is a regulatory subunit of CDK5, has participated in the regulation of human renal cancer." (PMID 31698798, 2019). "This treatment significantly decreased the tumor growth and number of HCC in DEN-challenged cdk5+/− mice." (PMID 31272499, 2019). "We finally obtained 35 RNA-seq or microarray datasets, which provided CDK5 expression value in HCC tissues (n=1864) and adjacent non-tumor tissues (n=1995), from online databases (GEO, ArrayExpress and Oncomine databases)." (PMID 29312535, 2017). "All together, these findings support the notion that the CDK5/p35/STAT3 pathway mediates the tumor-suppressive function of miR-26a, and that p35 deregulation through miR-26a plays an important role in tumor growth." (PMID 28640256, 2017).
tumor (continued). "Conversely, decreased CDK5 expression enhanced the recruitment of CD4+ T-cells to the tumor site in mice, and increased the tumor-free survival rate of the mice." (PMID 28077789, 2017). "The effect of miR-26a modulation on cell proliferation and tumor growth of DLBCL cells was accompanied by changes in p35 levels and CDK5 activity." (PMID 28640256, 2017). "In conclusion, inhibiting CDK5 is a multi-modal systemic approach to treat HCC, hitting angiogenesis, as well as the tumor cells themselves." (PMID 27027353, 2016). "Thus these observations suggested that CDK5 might function as a tumor promotor in human CRC." (PMID 27735944, 2016). "Our research has showed that high expression of CDK5 protein is significantly correlated with the aggressive characteristics (AJCC stage, tumor size, tumor differentiation and nodal metastasis) as well as poor survival of patients." (PMID 27735944, 2016). "After adjustment, tumor size, tumor differentiation, AJCC stage and CDK5 expression were identified as covariates." (PMID 27735944, 2016). "Since YAP is involved in growth of tumour cell spheroids in 3D models, we investigated spheroid size in nontargeting and CDK5 knockdown Huh7 cells." (PMID 39739588, 2025). "Collectively, these findings establish Cdk5 not merely as a cell-intrinsic oncogene, but as a crucial modulator of the tumor microenvironment." (PMID 41369365, 2025). "Additionally, inhibition of CDK5 increases ubiquitin E3 ligase FBXO22 levels, which degrades PD-L1 and makes tumor cells more sensitive to DNA damage." (PMID 38762484, 2024). "The anti-tumor effect of the concurrent ERK5 and CDK5 inhibition was due to decreased proliferation as shown by the decrease in Ki-67, a cell proliferation marker and increased cell death as shown by the increased number of Tunel-positive cells, a marker of apoptosis." (PMID 39271958, 2024). "Being a potent inhibitor of CDK2/CDK5, (S)-PHA533533 was developed as an anti-tumor drug and has been previously preclinically tested by administrating 7.5 mg/kg orally into a human ovarian A2780 xenograft mouse model twice a day for 20 days without any signs of toxicity." (PMID 38977672, 2024). "Similarly, CDK5 inhibition or knockdown initiates TRIM21-triggered degradation of PD-L1, suppressing tumorigenesis and tumor immunity." (PMID 37993880, 2023). "More specifically, several studies reported that increased expression of S100A6 promoted cell proliferation by regulating the expression of IL‐8, CDK5, CDK4, MCM7, Bcl2, and could be used as a marker of tumor aggressiveness in gastric cancers." (PMID 34857857, 2021). "Most important, CDK5 is directly involved in the degradation of the cell cycle inhibitor p21 and can enhance CDK2 activity, which might further promote tumor cell growth." (PMID 35002699, 2021). "CDK5 was increased in HCC and correlated with tumor growth, migration, and invasion." (PMID 31272499, 2019). "The patients with high expression of CDK5 and low expression of BIN1 showed similar prognosis, indicating that CDK5 could neutralize the tumor suppressing effect of BIN1 in clinical situation." (PMID 31496920, 2019). "We found that CDK5 (among 64%) transcripts were higher in tumor tissues than in noncancerous tissues." (PMID 31272499, 2019). "We combined in vitro studies with the analysis of a high number of tumor samples from different CRC stages and confirmed that Cdk5 is involved in CRC progression and that it could serve as a prognostic and predictive biomarker in this disease." (PMID 31614664, 2019). "We observed that HCC tumor tissues expressed significantly higher levels of CDK5 compared with noncancerous tissues in the majority of patients (63.3%)." (PMID 31272499, 2019). "To explore whether CDK5 was a functional target in ARNTL-mediated tumor cell proliferation suppression, we transiently infected the SUNE1 or HONE1 ARNTL-overexpression cells with PENTER-vector or PENTER-CDK5 plasmids." (PMID 30621723, 2019).
tumor (continued). "Expression of CDK5 in HCC tumor and paired adjacent noncancerous tissues from 90 patients were measured by Western blotting, immunohistochemistry, and real-time PCR." (PMID 31272499, 2019). "In addition, high expression level of CDK5 was correlated to the aggressive characteristics (American Joint Committee on Cancer (AJCC), tumor differentiation, tumor size and nodal metastasis) and poor survival of patients." (PMID 27735944, 2016). "This set of data indicates that the deletion of endothelial Cdk5 promotes non-productive angiogenesis, which resulted in reduced tumor growth." (PMID 26755662, 2016). "In endothelial-specific Cdk5 knockout mice, systemic treatment with roscovitine slightly but not significantly reduced tumor growth and decreased tumor cell proliferation as shown by Ki67 staining." (PMID 26755662, 2016). "Besides, Pearson's chi-square tests revealed that the expression of CDK5 was significantly correlated with AJCC (P=0.01), tumor differentiation (P=0.029), tumor size (P=0.001) and nodal metastasis (P=0.027)." (PMID 27735944, 2016). "For the first time this data associates altered CDK5 substrate phosphorylation with oncogenesis in some but not all tumour types, implicating altered CDK5 activity in aspects of pathogenesis." (PMID 26555036, 2015). "We measured the expression of miR-21, CDK5 and EMT markers in 60 HNSCC tumor samples." (PMID 26690371, 2015). "In addition to CDK4 and CDK5, cyclin-B/CDK1 may play a role in tumor cell spreading, motility, and invasion." (PMID 33723248, 2021). "Additionally, CDK5 and CDK5R1 were overexpressed in tumor tissues of patients with metastasis." (PMID 33240752, 2020). "In this context, P5 is a small peptide developed at the National Institutes of Health (NIH), comprising of 24 amino acids, which specifically inhibits the tumor-related CDK5/p25 activity without affecting the normal endogenous CDK5/p35 form, and respecting physiological activity of CDK5." (PMID 32708903, 2020). "Therefore, CDK5 directly targets nuclear p21CIP1 protein and activates CDK2, which represents an important role in the regulation of the cell cycle in the G1-S phase, and therefore, tumor growth is promoted." (PMID 31395805, 2019). "Furthermore, with Co-IP experiment, we found that CDK5 was correlated with the anergy of BIN1/c-MYC interaction, suggesting that CDK5 could neutralize the tumor-suppressing effect of BIN1 via inducing phosphorylation of c-MYC at Ser-62 site." (PMID 31496920, 2019). "Furthermore, the TTN-AS1/miR-142-5p/CDK5 axis might be used as potential biomarker in predicting prognosis of LUAD patients, and regarded as a novel target for anti-tumor therapies." (PMID 31363080, 2019). "To assess tumor proliferation relative to CDK5 expression, we performed immunohistochemical analysis for Ki-67, which identifies proliferating cells, on the tumor xenografts, but we could not measure any significant difference (data not showed)." (PMID 28640256, 2017). "The opposing relationships between CDK2/CDK3 (negative) and CDK5 (positive) with regulatory T cell populations suggest that selective CDK inhibition could serve dual therapeutic functions—blocking tumour proliferation while simultaneously enhancing anti‐tumour immunity." (PMID 40682474, 2025). "Increased activation of CDK5 was shown in patient tissues and in mice with a dox-inducible p25-GFP system found tumor development within 6 months of activation and showed MEN1 heterogeneity that did not affect the increased CDK5 expression." (PMID 37568572, 2023). "The inhibition of CDK5 expression was shown to reduce the formation of NICD, resulting in nonproductive angiogenesis and a decrease in tumor growth." (PMID 31093499, 2019). "The absence of Cdk5 induces the expression of PD-L1 transcriptional inhibitors (IRF2 and IRF2BP2), maintaining transcriptional repression of PD-L1 after IFN-γ stimulation, resulting in increased infiltration of CD4 T cells and promoting anti-tumor immune responses." (PMID 38762484, 2024).
neurodegenerative disease (101 papers, 2006 to 2025). A disorder of the central nervous system characterized by gradual and progressive loss of neural tissue and neurologic function. "One of the upregulated sites, S142, is a known target of Cdk5—a kinase frequently implicated in synaptic remodelling and neurodegenerative diseases." (PMID 41268362, 2025). "Taken together, aberrant activation of Cdk5 is associated with development and progression of neurodegenerative diseases." (PMID 38842132, 2024). "Though, overstated Cdk5 is implicated in different types of neurodegenerative diseases including PD which is a common neurodegenerative disease characterized by degeneration of dopaminergic neurons in the SNpc." (PMID 38842132, 2024). "Low CDK5 activity leads to several neurodevelopmental disorders, and deregulated CDK5 activity is strongly associated with pathological changes in multiple neurodegenerative diseases." (PMID 37993880, 2023). "CDK5 is a proline-oriented Ser/Thr protein kinase which can phosphorylate tau, and μ-calpain can truncate p35 into p25, resulting in abnormal activation of CDK5 and the death of neurons associated with a variety of neurodegenerative diseases." (PMID 35501719, 2022). "The abnormal CDK5 expression or activity has been closely associated with neurotoxicity in various neurodegenerative diseases, including AD, HIV neurotoxicity, and prion-related encephalopathies." (PMID 33401710, 2021). "Aberrant Cdk5 activity caused by p25 accumulation contributes to the pathogenesis of various neurodegenerative diseases." (PMID 34814918, 2021). "Hyper-activation of CDK5 is seen in a number of neurodegenerative diseases where it is believed to play a causative role in the degenerative process." (PMID 31910742, 2020). "Numerous studies have implicated dysregulation of Cdk5 activity in neurodegenerative diseases due to its role in regulating cytoarchitecture, axonal transport, and synaptic activity." (PMID 29227247, 2017). "p25/Cyclin-dependent kinase 5 (Cdk5) has been implicated in the pathogenesis of several neurodegenerative diseases, including AD." (PMID 26317805, 2015). "Cyclin-dependent kinase 5 (Cdk5) is essential for brain development and function, and its deregulated expression is implicated in some of neurodegenerative diseases." (PMID 24495352, 2014). "This deregulated Cdk5/p25 activity has been linked to be a causative factor of various neurodegenerative diseases." (PMID 25383141, 2014). "Deregulation of CDK5 activity by p25 has been involved in numerous neurodegenerative diseases, while Cdk5-loss-of-function studies have revealed its pro-survival function in neurons under normal or stress conditions." (PMID 23029270, 2012). "Aberrant phosphorylation caused by the deregulated activity of cyclin dependent kinase 5 (Cdk5) has been closely associated with various neurodegenerative diseases like AD, ALS, HD, and PD." (PMID 21941533, 2011). "According to NCBI Entrez gene annotation, it was reported that the deregulation of gene CDK5 causes neuronal death and neurodegenerative diseases." (PMID 21143783, 2010). "Dysregulation of cyclin-dependent kinase 5 (CDK5) has been implicated in several neurodegenerative diseases, including Alzheimer's." (PMID 21118505, 2010). "In fact, phosphorylated neurofilaments and their associated kinases, most of which are represented by CDK5, were found in protein aggregates typical of neurodegenerative diseases." (PMID 18053171, 2007). "The active CDK5-p35 complex is strongly involved in neurofilament phosphorylation and its aberrant hyperactivity has been shown to be implicated in neurodegenerative diseases." (PMID 18053171, 2007). "Cyclin dependent kinase 5 (CdK5) is a proline-direct protein kinase that is most active in the CNS and has been implicated in certain neurodegenerative diseases." (PMID 16842618, 2006). "CDK5 has been implicated in several neurodegenerative diseases, including AD, PD, and DLB." (PMID 40869369, 2025).